CD34 (CD34 molecule)
Diseases named in the same sentence as CD34 in open-access papers (continued):
Sharing a sentence is not in itself a finding about the gene and the disease.
leukemia (continued). "To evaluate this possibility, we knocked down TAF1 in the non-AE-expressing K562 leukemia cell line and in human CD34+ CB cells." (PMID 31664040, 2019). "On the other hand, the use of the antimicrobial tigecycline selectively killed leukemia CD34+CD38- cells without affecting normal hematopoietic cells through the inhibition of mitochondrial translation." (PMID 30967773, 2019). "Also, AML CD34+ cells, express detectable activity of NF-κΒ36, reinforcing the notion that NF-κΒ signaling has a pivotal role in the development of AML leukemia." (PMID 31727944, 2019). "The recent inclusion of CD26 as a putative leukemia stem cell marker in CML suggests that going forward, the CD34+/CD38–/CD26+ compartment may be most appropriate for identifying a resistance signature governing deep responses." (PMID 29707154, 2018). "CD25-negative Lin–CD34+ cells recapitulated leukemia, but the engrafted leukemic cells did not express CD25." (PMID 30550585, 2018). "In this setting, high numbers of both γδ T-cells (Vδ1 and Vδ2) and NK cells are infused together with CD34+ HSC and may contribute to rapid control of infections and leukemia relapse." (PMID 29867961, 2018). "Moreover, it has been shown that introducing genetic changes to CD34+ human hematopoietic progenitor cells before injecting these cells into immunodeficient mice could generate a humanized mouse leukemic model that has recapitulating features of primary leukemia." (PMID 29850623, 2018). "Even though the mice did not develop leukaemia, they observed a transient expansion of CD34+ cord blood cells expressing MLL-AF4 upon FLT3 activation." (PMID 28819864, 2018). "CD34+CD19−, CD34+CD19+ and CD34−CD19+ fractions all engrafted robustly and could initiate leukaemia development with a phenotype similar to what was observed in patients and a mean latency of 11.7 weeks." (PMID 28819864, 2018). "Our data indicate that AF4-MLL transiently enhances long-term hematopoietic reconstitution in immunodeficient mice, but is not sufficient to initiate leukemia in primary neonatal CD34+HSPCs." (PMID 29137234, 2017). "These CD34+/CD38− leukemia stem-like cells displayed positivity of the myeloid markers CD13 (99.1%), CD33 (98.6%), and CD123 (93.7%), suggesting that certain myeloid features remain in these sorted CD34+/CD38− KG1α cells." (PMID 28518151, 2017). "Activity of STAT5 is often associated with leukemia stem cells phenotype and therefore it has not been surprising in this context to observe that several sensitive AML cells were CD34 positive." (PMID 28422713, 2017). "Interestingly, the expression of either HOXA9, a canonical downstream target for MLL-rearranged leukemia or ZNF521 have been shown to be restricted in CD34+ progenitor cells." (PMID 28412727, 2017). "Thus, chidamide synergistically enhanced chemotherapy agent-induced cell apoptosis in leukemia stem-like cells and primary refractory or relapsed AML CD34+ cells." (PMID 28814980, 2017). "Downregulation of Nrf2 and phosphorylation of JNK induced by DS/Cu were markedly blocked by NAC in CD34+CD38− KG1α cells, suggesting that ROS might act upstream of the Nrf2 and JNK pathways in leukemia stem-like cells treated with DS/Cu." (PMID 28518151, 2017). "When ALL cells were sorted and assessed in functional assays, all 4 subpopulations (CD34+/CD99+, CD34+/CD99-, CD34-/CD99+ and CD34-/CD99-) could proliferate in vitro and establish leukemia in NSG mice." (PMID 27764235, 2016). "Interestingly, CD34 and CD44 are also known as cancer stem cell markers, which are unique for specific types of cancer, for example, CD34 in leukemia and sarcoma, whereas CD44 in colon and breast cancer." (PMID 27066458, 2016).
leukemia (continued). "To investigate whether miR-203 is down-regulated in leukemia and regulates biological functions of LSCs, we isolated CD34 + /CD34− cells from blood samples of 50 leukemia patients and collected 15 blood specimens from healthy subjects." (PMID 26847520, 2016). "As CD34 regulates cell migration and adhesion, we studied whether the distinct leukemia development activity between CD34+ and CD34− cells from T-ALL1 and T-ALL2 was based on a differential homing capacity." (PMID 27191650, 2016). "As leukemia development relies on clonal selection in xenograft, we hypothesized that the difference in aggressiveness between CD7+/CD34+ and CD7+/CD34− cells relates on the presence in both sub-fractions of distinct genetic subclones." (PMID 27191650, 2016). "By screening different blood cancers, we have observed that this activity is not always restricted to CD34+ leukemic cells, and can be overexpressed in CD34 negative leukemia." (PMID 27732563, 2016). "We sorted the CD34+CD38- cells from the AML cell line KG1a and the CML cell line KU812, as LSCs of myelogenous leukemia are considered to be enriched in this fraction, which was also previously reported in leukemia cell lines including KG1a." (PMID 26784514, 2016). "Here, we investigated the growth-suppressive effect of this compound in AML cells and found that OTS514 has significant anti-leukemia activity in primary blasts but not in CD34+ cells derived from healthy donors." (PMID 26450903, 2015). "While there is limited data on the phenotype of the stem cell / leukemia initiating compartment in human APL there is some data to suggest that this population, at least in a mouse model, resides in promyelocytes that are CD34(+), c-kit(+)and FcgammaRIII/II(+)." (PMID 25822503, 2015). "CD34+/CD123+/CD38- populations enriched for leukemia-initiating progenitors, but not CD34+ normal hematopoietic progenitors, are highly susceptible to this regimen." (PMID 25914884, 2015). "In our study, CD82 inactivated p38 MAPK and downregulated expression of p16 in leukemia cells, suggesting that CD82 might inhibit senescence in CD34+/CD38− AML cells via inactivation of p38 MAPK signaling and suppression of p16 expression." (PMID 25955299, 2015). "The results indicated reasonably viable number of hematopoietic stem cells in presence of leukemia microvesicles which still expressed more than 90 % CD34 and CD45 markers without differentiation." (PMID 26862318, 2015). "From our results showing the correlations between Sp1 and c-Myc levels and survivin expression in CD34+ AML patients, inhibitors of Sp1 and c-Myc may provide novel therapeutic strategies for the treatment of leukemia." (PMID 25890196, 2015). "Aberrantly high expression of TWIST-1 in leukemia stem/progenitor cells could be confirmed when we analyzed the expression of TWIST-1 in highly purified leukemic CD34+CD38−, CD34+CD38+ and CD34− cells isolated from patients with AML (n = 9) and CML (n = 9)." (PMID 26023795, 2015). "Subsequent studies demonstrated that the tumorigenic potential was not restricted to these markers as human CD34+/CD38+ leukemia cells also produced tumors in mice." (PMID 25080108, 2014). "Here, we demonstrate in a wide range of primary patient samples and patient samples previously passaged through mice that leukaemia-propagating cells are found in all populations defined by high or low expression of the lymphoid differentiation markers CD10, CD20 or CD34." (PMID 23229821, 2013). "To study the effects of leukemia cells on BMSCs, we co-cultured BMSCs from healthy donors with three different leukemia cell lines, TF-1α, TF-1 and K562, that were selected according to their phenotypes: CD34+/CD38-, CD34+/CD38+ and CD34-, respectively." (PMID 24304929, 2013). "In contrast, MLL/AF4, which also enhances CD34+ progenitor cell expansion, did not induce leukemia even after intra-bone marrow transplantation into NOD/SCID mice." (PMID 24348510, 2013).
leukemia (continued). "Initially, as the specific surface markers CD34 and CD38 had been extensively validated in the identification of normal hematopoietic stem cells, these molecules were used as markers in the original studies of leukemia stem cells." (PMID 22359637, 2012). "Subsequently, some leukemia-initiating cells (L-ICs) have been found in the CD34 negative marrow fractions." (PMID 22876360, 2012). "In another leukemia subtype that is prone to early relapse, pediatric T cell acute lymphoblastic leukemia (T-ALL), serially transplantable LIC were found to be enriched in CD34+CD4− and CD34+CD7− fractions of newly diagnosed patient samples." (PMID 22768113, 2012). "Consistent with this interpretation of our data are for example findings showing that blast cell numbers or a high number of CD34+ in the BM of AML patients correlated with shorter survival, supporting a relationship between higher leukemia-initiating cell burden and poor prognosis." (PMID 22363661, 2012). "In addition, our microarrays showed overexpression of homeobox genes in primary human CD34+ cells expressing MLL-AF9, consistent with previous results showing overexpression of these genes in both mouse and human leukemias with MLL fusions." (PMID 20805992, 2010). "When analyzing the HSC and MPP (CD34+CD38+) compartments, in many cases (6 out of 10) a strong shift from the MEP/CMP compartments towards the GMP was observed, possibly highlighting the myeloid character of the leukemias that were studied." (PMID 19956772, 2009). "Indeed, clonal subcultures derived from single B-ALL cells give rise to subpopulations with disparate CD34 and CD38 expression within hours and ultimately reproduce a heterogeneous leukemia regardless of the initial CD34 and CD38 immunophenotype." (PMID 41295979, 2026). "For example, in AML, only a subpopulation of CD34+/CD38− CSCs could reconstitute the leukaemia model in immunodeficient mice, whereas differentiated CD34− cells lacked tumourigenic potential." (PMID 40665579, 2025). "RXFP1 expression is markedly elevated in leukemia cells, with 2.71-fold increases in acute myeloid leukemia (AML) and 3.31-fold increases in chronic myeloid leukemia (CML) compared with control populations (CD34+/CD38- stem cells and CD34+/CD38+ progenitor cells)." (PMID 41196672, 2025). "Collectively, these results demonstrate that circulating EVs from AML patients may trigger CD34+ AML cells toward an increase in both mitochondrial potential and GSH levels, reducing ROS levels and showing a leukemia-dependent mechanism partially reverted by GPX4 inhibition." (PMID 39738118, 2024). "In contrast, the proliferation of normal human CD34 + cells was unaffected under the conditions where that of P31/FUJ cells was severely impaired, suggesting that the combined inhibition of MOZ/MORF KATs and DOT1L KMT selectively induces differentiation of CALM-AF10 leukemia cells." (PMID 37031220, 2023). "Moreover, a higher expression in leukemic cells with more immature immunophenotypes (CD34+/CD38- and CD34+/CD33-) was observed, and the same subgroups also showed a reduced mitoxantrone retention compared to more mature leukemia cells, confirming the efflux activity of ABCG2." (PMID 37108308, 2023). "However, MYLS22 did not change the proportion of CD34+CD38- leukemic cell population known to be enriched in leukemia-initiating cells." (PMID 36739349, 2023). "AML-CD34+ showed higher CDK6-AS1 levels and mitochondria content than the more differentiated CD34− AML blasts, confirming that CDK6-AS1 overexpression positively correlated with mitochondrial biogenesis and mass in leukemia cells, especially in the CD34+ subpopulation." (PMID 36827549, 2023). "The identification of a very minor fraction of leukemia marrow cells that have a primitive Lin−, CD34+, CD19−, CD33−, CD38− phenotype and that contained the patient-specific leukemia karyotype suggests that B-cell precursor ALL may arise in a more primitive cell." (PMID 35216407, 2022).
leukemia (continued). "However, the blasts in AML with monocytic differentiation (e.g., acute monocytic/monoblastic leukemia, AML with mutated NPM1), acute erythroid leukemia, and acute megakaryocytic leukemia are typically negative for CD34." (PMID 36245043, 2022). "To further investigate the strength of our adoptive immunotherapy, we sought to evaluate whether CAR.CD123-NK cells were able to recognize and eliminate CD34+CD38− AML cells, which are known to represent the leukaemia-initiating cell compartment characterized by high resistance to chemotherapy." (PMID 36335396, 2022). "In leukemia cell lines HL60 and Jurkat, and CD34+ progenitor cells, induction of the Wnt/β-catenin signal increases the expression of the RUNX1 P1 isoform, which may be critical for leukemia onset and progression; in colon cancer cells, RUNX2 was found to be upregulated by the same pathway." (PMID 36429115, 2022). "ARV-825 resulted in reduced BETP-dependent transcription of chemokine receptors, indicated by downregulation of surface CXCR4 and CD44 in leukemia stem cell populations, thereby reducing CD34+CD38– putative leukemia progenitor cell populations without affecting healthy BM–derived progenitor cells." (PMID 33466790, 2021). "Furthermore, LINC01257 expression was absent in healthy progenitor CD34+ stem cells, MSCs and other subtypes of leukemia, highlighting the specificity of LINC01257 for AML and the value of its targeting as a precision medicine approach for this disease." (PMID 34683974, 2021). "Understanding the function of the CD9 receptor in normal and malignant CD34+ and VSELs, along with its relationship with the CXCR4/SDF-1 pathway, will enable advances in the field of adult pluripotent cell usage in regenerative medicine and in their role in leukemia." (PMID 33918035, 2021). "The origin of cancer directly from the normal stem cell was mainly supported by reports that identified the CD34+/CD38- tumor subpopulation as the fraction that can initiate leukemia upon transfer to nonobese diabetic-severe combined immunodeficiency (NOD/SCID) recipient mice." (PMID 34736527, 2021). "Collectively, these data indicate that MLL-AF9 can immortalize CD34+ cells of both neonatal as well as adult origin in vitro, whereas MLL-AF4 can solely immortalize cells of neonatal origin comparable to KMT2Ar patient leukemia, as the portion of MLL-AF4 leukemia in adults is very rare." (PMID 32517300, 2020). "In contrast, as primary AML patient samples contained fewer leukemia-initiating cells, we could coculture MSCs and AML cells in direct contact without observing any contamination from AML cells after sorting CD34+ cells and assessing their ex vivo or in vivo functionalities." (PMID 32364536, 2020). "Interestingly, we also observed the expression of TERF1-tsi in (healthy)-donor-derived CD34+-HSCs but not in the CD34+-KG1 cell line or other leukemia cell lines such as HL60 or U937 (unpublished observations)." (PMID 31877678, 2019). "A study was performed by The Acute Leukemia and Pediatric Diseases Working Parties of the European Blood and Marrow Transplantation (EBMT) Group which analyzed the outcome of a large cohort of children with acute lymphoblastic leukemia (ALL) given a CD34+ positively selected haplo HSCT." (PMID 29850617, 2018). "While in this patient, leukemia cells were negative for CD56 or CD34." (PMID 30200136, 2018). "Importantly, miR-375 can not decrease colony formation in normal CD34+ HSPC cells, suggesting that restoring miR-375 expression inhibits self-renew of leukemia stem cell but not of normal CD34+ cells." (PMID 29439669, 2018). "Importantly, expression of AF4-MLL in primary neonatal CD34+ HSPCs failed to render any phenotypic or hematological sign of disease, and was therefore not sufficient to initiate leukemia within a 36-week follow-up." (PMID 29137234, 2017).
leukemia (continued). "Similarly, a diagnosis of AML should be considered with a non-clonal test result, particularly if the leukemia lacks expression of B or T cell markers with flow cytometry and is positive for the stem cell marker CD34 and negative for MHCII." (PMID 28620611, 2017). "However, there have been cases that lacked CD34 or CD38 protein but still had leukemia initiating capacity in B-ALL suggesting the restrictive of these two markers." (PMID 28018598, 2016). "Indeed we have found that 3/3 tested short term engrafting T-ALLs contain a predominant genetically defined clone endowed with xenograft leukemia development capacity that segregates with CD7+/CD34+ and CD7+/CD34− cell fractions, although the latter fraction was poorer in such function." (PMID 27191650, 2016). "In CD7+/CD34+-derived leukemia, the proportion of IKZF1del positive cells raised to 100% in virtually all (5+/6 mice, 2 experiments) mice, indicating the reproducible selection of the IKZF1del clone, while it was barely detectable in CD7+/CD34−-derived xenografts (0.01% in 2/4 mice, 2 experiments)." (PMID 27191650, 2016). "Overall, our work reveals that T-ALL cell subpopulations isolated based on cell surface markers, such as here CD34 and CD7 expression, and bearing differential leukemia initiating activity may contain distinct clones, with genetic and probably also, but yet not depicted, epigenetic differences." (PMID 27191650, 2016). "Also, we demonstrated that treatment with Smac mimetic has no adverse effect on colony formation of normal human CD34+ hematopoietic cells freshly isolated from healthy human donors at concentrations that are cytotoxic against leukemia cells." (PMID 27385100, 2016). "Similarly three samples classified as CD34-positive leukaemia with dim or negative staining for leukocyte antigens on FC were assigned to a T-cell lineage by PARR." (PMID 27863542, 2016). "With CD34+CD38−CD26+ as the phenotype, CML-LSCs could be detected on flow cytometry in most of our patients with UMRD, which was consistent with the notion that the residual leukemia cells after TKI treatment are insensitive stem cells." (PMID 27533462, 2016). "Together, these results suggest that CRAds armed with therapeutic transgenes such as Beclin-1 could eradicate leukemia stem cells although the exact effects of SG511-BECN on CD34+ leukemic stem cells has not been determined." (PMID 23765161, 2013). "Importantly, CD34+ leukemia progenitor cells but not normal CD34+ stem/progenitor cells were lysed by Aurora-A kinase-specific CTLs." (PMID 24427158, 2013). "However, overexpression of the MLL-AF4 fusion gene in human CD34+ cells is not sufficient to initiate leukemia." (PMID 22745659, 2012). "Furthermore, NK-cells have been shown to be able to kill CD34+ CML stem cells, which also may play a role in the graft vs. leukemia effect after allogeneic transplantation." (PMID 21857985, 2011). "Furthermore, CD34+CD38+ cells failed to produce leukemia in immunodeficient mice." (PMID 39335624, 2024). "Additionally, some leukemias did not contain any LICs in the CD34+CD38− fraction." (PMID 37735675, 2023). "Given the focus on CD34-expressing leukemia, the results may not be generalizable to other immunophenotypes of AML, and the sample numbers may have limited our ability to identify and verify some prognostic transcripts – especially those with modest clinical effect sizes." (PMID 36927800, 2023). "In human Mtb-infectedSP+ and Lin–CD34+ pHSCs we similarly detected both SigA expression and the expression of the dormancy regulator genes, DosR, c-lat and hspX, while replicating Mtb isolated from an infected human monocytic leukemia cell line did not express these genes." (PMID 28046053, 2017).